SLAIN1 (SLAIN family member 1)
Description:
Microtubule plus-end tracking protein that might be involved in the regulation of cytoplasmic microtubule dynamics, microtubule organization and microtubule elongation.
Synonyms: C13orf32; FLJ30046
Tractability: PROTAC: ubiquitination databases record sites on it; its protein half-life has been measured.
Gene: Protein-coding gene on chromosome 13 (77,697,687 to 77,764,242, forward strand). Ensembl gene ENSG00000139737.
Subcellular location: Cytoplasm, cytoskeleton
Gene Ontology:
Molecular function: protein binding
Biological process: cytoplasmic microtubule organization; microtubule nucleation; positive regulation of microtubule polymerization
Cellular component: microtubule plus-end; cytoskeleton
Genetic constraint (gnomAD): Loss-of-function variants: 13 observed, 44.92 expected, observed/expected ratio (o/e) 0.29, 90% interval 0.19 to 0.46. The synonymous counts are far from expectation, so gnomAD's model fits this gene poorly and the ratio says little. Missense variants: 625 observed, 614.71 expected, observed/expected ratio (o/e) 1.02, 90% interval 0.95 to 1.09. Synonymous variants: 316 observed, 259.24 expected, observed/expected ratio (o/e) 1.22, 90% interval 1.11 to 1.34.
Homologues: Orthologues: macaque SLAIN1 (98% identical), dog SLAIN1 (94% identical), rabbit SLAIN1 (94% identical), pig SLAIN1 (92% identical), chimpanzee SLAIN1 (91% identical), rat Slain1 (85% identical), mouse Slain1 (85% identical), guinea pig SLAIN1 (76% identical), tropical clawed frog slain1 (60% identical), zebrafish slain1a (43% identical). Paralogues in human: SLAIN2 (34% identical).
Diseases named in the same sentence as SLAIN1 in open-access papers:
SLAIN1 is named in the same sentence as 10 diseases in open-access papers, as found by Europe PMC text mining. Sharing a sentence is not in itself a finding about the gene and the disease. The quoted sentences say what the papers report.
Intellectual disability (2 papers, 2017 to 2021). "Recently, SLAIN1 was identified as a candidate gene for intellectual disability." (PMID 33433033, 2021). "Furthermore, loss of function mutations of SLAIN1 (as well as of MAPK8, which was also identified as zDABM-protein in our screening) are associated with intellectual disability." (PMID 28882895, 2017).
astrocytoma (1 paper, 2022). "Validation of 6 biomarkers with the highest importance score in TCGA and CGGA cohorts revealed that HS3ST1, and CNN3 were overexpressed in astrocytoma, while SLAIN1, ABTB2, TRIM67 and DRG2 were overexpressed in oligodendroglioma." (PMID 35287567, 2022).
heart failure (1 paper, 2025). Inability of the heart to pump blood at an adequate rate to meet tissue metabolic requirements. "MR analysis identified significant causal associations between the genes implicated in BW loss (ADD3, HSPA12A, SLC18A2, PDZD8, DUSP5, CASP7) as well as EF% and LV volumes (GPC6, UGGT2, SLAIN1, POU4F1, MBNL2) in BXD mice post-DOX and heart failure (HF) outcomes in humans." (PMID 40321772, 2025).
hepatocellular carcinoma (1 paper, 2021). A malignant tumor that arises from hepatocytes. "Simultaneously, we predict that two genes (AUTS2 and SLAIN1) regulated by miR-1246 are very lowly expressed in hepatocellular carcinoma, and the high expression of the AUTS2 gene among them is correlated with the longer overall survival time of hepatocellular carcinoma patients." (PMID 34163524, 2021). "Based on these findings, a potential miR-497-mRNA or miR-1246-mRNA regulatory network can be established, namely, miR-497-ARL2/UBE2Q1/PHF19/APLN/CHEK1/CASK/SUCO/CCNE1/KIF23, or miR-1246-AUTS2/SLAIN1, which contributes to the occurrence and development of hepatocellular carcinoma." (PMID 34163524, 2021).
idiopathic pulmonary fibrosis (1 paper, 2023). Idiopathic pulmonary fibrosis (IPF) is a nonneoplastic pulmonary disease that is characterized by the formation of scar tissue within the lungs in the absence of any known cause. "In this study, we identified four potential biomarkers (FHL2, HPCAL1, RNF182, and SLAIN1) and evaluated the potential pathogenic role of SLAIN1 in idiopathic pulmonary fibrosis." (PMID 37783761, 2023). "Finally, we assessed the potential pathogenic role of the biomarker (SLAIN1) in the development of idiopathic pulmonary fibrosis using mouse and cellular models." (PMID 37783761, 2023). "Finally, we sought to understand the potential pathogenic role of the biomarker (SLAIN1) in idiopathic pulmonary fibrosis using a mouse model and cellular model." (PMID 37783761, 2023). "In summary, this research successfully pinpointed four promising biomarkers (FHL2, HPCAL1, RNF182, and SLAIN1) and investigated the potential involvement of SLAIN1 in the pathogenesis of idiopathic pulmonary fibrosis." (PMID 37783761, 2023). "FHL2, HPCAL1, RNF182, and SLAIN1 were identified as biomarkers of idiopathic pulmonary fibrosis using LASSO logistic regression, RF, and SVM-RFE algorithms." (PMID 37783761, 2023). "In summary, our comprehensive examination of SLAIN1 expression both in vivo and in vitro strengthens our understanding of its potential role as a biomarker and its involvement in the pathogenesis of idiopathic pulmonary fibrosis." (PMID 37783761, 2023). "Finally, we detected the expression level of SLAIN1 to assess its potential role in the pathogenesis of idiopathic pulmonary fibrosis using a mouse model and cellular model." (PMID 37783761, 2023). "qPCR and western blotting analysis suggested that SLAIN1 might be a signature for the diagnosis of idiopathic pulmonary fibrosis." (PMID 37783761, 2023). "Furthermore, we confirmed the expression level of SLAIN1 in the pathogenesis of idiopathic pulmonary fibrosis using both a mouse model." (PMID 37783761, 2023).
ovarian carcinoma (1 paper, 2022). A malignant neoplasm originating from the surface ovarian epithelium. "Hsa_circ_0000497 and hsa_circ_0000918 may regulate ovarian cancer metastasis via their host genes, although neither SLAIN1 nor GMIP is reported in tumor metastasis." (PMID 35538537, 2022).
SLAIN1 also shares sentences with these, for which no sentence is quoted: cancer (1 paper); oligodendroglioma (1); tumor (1); Wilms tumor (1).